CYP2D6 (cytochrome P450 family 2 subfamily D member 6 (gene/pseudogene))
Diseases named in the same sentence as CYP2D6 in open-access papers (continued):
Sharing a sentence is not in itself a finding about the gene and the disease.
breast carcinoma (continued). "The plasma steady-state concentration of (Z)-endoxifen in drug-treated breast cancer patients is strongly associated with the number of functional CYP2D6 alleles." (PMID 26232141, 2015). "The main objective of this study was to determine the CYP2D6 allele and genotype frequencies and their associations with (Z)-endoxifen-directed tamoxifen metabolism in Polish breast cancer patients treated with the standard daily dose of 20 mg of tamoxifen." (PMID 26232141, 2015). "As tamoxifen-induced reductions in percent mammographic density (PMD) have been linked to the risk and prognosis of breast cancer, we conducted a candidate gene study to investigate the association between germline CYP2D6 polymorphisms and PMD change." (PMID 24088226, 2013). "In women with breast cancer, slow metabolizers of CYP2D6 (carrier state of slow allele CYP2D6*4), endoxifen is formed in the lower levels, and remission period is lower." (PMID 23663439, 2013). "Twenty-five studies of 13,629 individuals were identified, of which 22 investigated the association of CYP2D6 genotype with outcomes in breast cancer women all receiving tamoxifen treatment (“treatment-only” design)." (PMID 24098545, 2013). "We investigated the evidence base on the association between CYP2D6 genotype and clinical outcomes following tamoxifen treatment for breast cancer." (PMID 24098545, 2013). "In this study, we explored the association between CYP2D6 metabolizer phenotype and mammographic density change, using breast cancer cases from a population-based breast cancer case–control study conducted in Sweden between 1993 and 1995." (PMID 24088226, 2013). "Criteria for inclusion were studies reporting breast cancer outcomes in patients treated with tamoxifen and genotyped for polymorphisms in the CYP2D6 gene." (PMID 24098545, 2013). "We investigated the evidence of the association between CYP2D6 genotype and response to tamoxifen treatment in individuals with breast cancer by conducting a systematic review and meta-analysis." (PMID 24098545, 2013). "In breast cancer patients who were treated with tamoxifen, the CYP2D6 phenotype was associated with survival and the concentration of the active tamoxifen metabolite, endoxifen." (PMID 23207012, 2012). "CYP2D6 has different variants and poor metabolizers and severely impaired CYP2D6 are suggested to be associated with high recurrence of breast cancer." (PMID 25562699, 2012). "Corroborating this notion, CYP2D6 polymorphisms responsible for reduced CYP2D6 activity were associated with worse breast cancer outcomes in postmenopausal estrogen receptor-positive patients treated with tamoxifen." (PMID 23346096, 2012). "The recognition that functional CYP2D6 polymorphisms affect tamoxifen pharmacokinetics has motivated the attempts of using CYP2D6 genotyping for predicting breast cancer outcomes." (PMID 23346096, 2012). "Neither study demonstrated an association between the risk of breast cancer recurrence and CYP2D6 phenotype." (PMID 21970596, 2011). "The potential effect of CYP2D6 genetic variants on clinical response in tamoxifen-treated breast cancer patients has recently gained much interest." (PMID 21364577, 2011). "Postmenopausal women with the homozygous CYP2D6*4 genotype (PM) using tamoxifen tend to have a higher risk of breast cancer recurrence than EMs." (PMID 20700120, 2010). "Patients lacking CYP2D6 enzyme function (PM) had an almost twofold increased risk of breast cancer recurrence compared with patients with two functional CYP2D6 alleles (EM)." (PMID 27713292, 2010). "For example, in our pharmacokinetics study of Tamoxifen in breast cancer patients, 35 CYP2D6 alleles were investigated from more than 70 known CYP2D6 polymorphisms." (PMID 20467479, 2010). "We investigated the association of CYP2D6 variants with breast cancer specific survival (BCSS) in breast cancer patients receiving tamoxifen." (PMID 20731819, 2010).
breast carcinoma (continued). "Summary of clinical studies that have evaluated the association between CYP2D6 genotype and tamoxifen-related clinical outcome in early breast cancer patients." (PMID 27713292, 2010). "Women with the dysfunctional CYP2D6 alleles *4, *5, *10 and *41 had an increased risk of breast cancer recurrence and worse relapse-free survival rates." (PMID 20700120, 2010). "We have examined all the available evidence on CYP2D6 variants and outcome for breast cancer patients treated with adjuvant tamoxifen including our own data presented here." (PMID 20731819, 2010). "Although there is good pharmacokinetic evidence to support the existence of PM and IM CYP2D6 variants, the evidence linking these variants to clinical outcome in tamoxifen-treated breast cancer patients is much weaker." (PMID 20731819, 2010). "Previous studies have shown that adjuvant tamoxifen users with a PM status (only based on CYP2D6 genotype) have an increased risk of breast cancer recurrence and mortality." (PMID 20700120, 2010). "Similar phenomenon of CNVs' effect on genotype-association has been found in the locus of CYP2D6 in breast cancer, and it has been pointed out that CNVs in this locus should be assessed before genotype-association analysis." (PMID 20808825, 2010). "In the selected population, the heterozygous CYP2D6 genotype was also found to be associated to a protective effect against breast carcinoma." (PMID 18423013, 2008). "A significant association was found between CYP2D6 (G/G) wild type and breast carcinoma risk only in postmenopausal patients (p = 0.04)." (PMID 18423013, 2008). "The analysis confirmed that individuals with PM phenotypes had an increased risk of breast cancer recurrence and/or mortality associated with reduced CYP2D6 activity, while IM showed modest effects in European populations but larger, likely biased, effects in Asian cohorts." (PMID 41295207, 2025). "Tamoxifen relies on CYP2D6 to generate the active metabolite endoxifen; potent CYP2D6-inhibiting antidepressants such as paroxetine can depress endoxifen concentrations by up to 72%, an interaction linked to increased breast-cancer mortality when exposure overlap exceeds 6 months." (PMID 40932868, 2025). "Our study demonstrates that carriers of CYP2D6*4 have a higher risk of both all-cause and breast cancer-specific mortality and indicates that longer follow-up time may be crucial to determining impact." (PMID 40452016, 2025). "Notably, several investigations involving CYP2D6 polymorphisms have contributed to the refinement of tamoxifen-based therapy in breast cancer patients, enabling a pharmacogenomically guided, individualized treatment strategy." (PMID 40723371, 2025). "Therefore, this prospective observational study aimed to investigate the relationships between the CYP2D6 polymorphisms and plasma concentration of tamoxifen/endoxifen in Chinese patients with breast cancer treated with tamoxifen." (PMID 40050768, 2025). "Focusing on the subgroup of patients with tamoxifen as their only systemic treatment did not reveal any statistically significant association between CYP2D6 activity and breast cancer recurrence (aHR 1.39, 95% CI 0.99; 1.96) or breast cancer mortality (aHR 1.88, CI 0.98; 3.60)." (PMID 40600576, 2025). "In addition, SSRIs with weak CYP2D6 inhibition were associated with lower overall and breast cancer specific survival." (PMID 40452016, 2025). "Another concern is that the low incidence of relapses and breast cancer-related deaths might have rendered the study underpowered for detection of an association between low CYP2D6 activity and clinical outcomes." (PMID 40600576, 2025). "Owing to the high prevalence of the CYP2D6*17 variant among the black Zimbabwean population, the results of this study might provide benefit for breast cancer patients upon the introduction of personalised TAM therapy in Zimbabwe." (PMID 36836506, 2023).
breast carcinoma (continued). "Also, we must consider the copy number variants of CYP2D6 such as *2 × 2 which increases the function of the enzyme and can affect the drug metabolism of both tramadol and tamoxifen, especially in breast cancer patients within the region." (PMID 37623436, 2023). "However, the association between CYP2D6 genotype and clinical outcome in patients with breast cancer treated with tamoxifen is controversial." (PMID 35501919, 2022). "However, debate continues on the adverse clinical outcomes associated with the use of CYP2D6 inhibitor antidepressants in breast cancer patients receiving tamoxifen." (PMID 36199859, 2022). "Our study aimed at gaining insights into the frequencies of the most clinically relevant CYP2D6 alleles in a cohort of Syrian breast cancer patients and establishing the clinical utility of CYP2D6 genotyping in the prediction of tamoxifen efficacy and occurrence of its side effects." (PMID 36243690, 2022). "in 2013, where the CYP2D6*10 minor allele frequency in a Sri Lankan population (n = 75) was reported to be 39%, similar to the 37.9% obtained in the cohort of 70 hormone receptor positive breast cancer patients genotyped in this study." (PMID 35296326, 2022). "For instance, polymorphisms in the serotonin transport genes are associated with increased PONV in women with breast cancer, even before receiving chemotherapy, while there is a tendency for individuals categorized as CYP2D6 poor metabolizers to experience PONV." (PMID 35847822, 2022). "In 2017, a meta-analysis of 15 studies of breast cancer in Asia (total of 1794 individuals) revealed an association of the rs1065852 *10/*10 (TT) polymorphism in the CYP2D6 gene with worse disease-free survival and relapse in women receiving adjuvant treatment with tamoxifen dosage of 20 mg/day." (PMID 36553620, 2022). "The aim of this study was to apply the model to virtual breast cancer populations capturing the respective CYP2D6 allele frequencies, simulate tamoxifen standard dosing for each biogeographical group, and determine the frequency of patients with subtarget CSS,min ENDX." (PMID 34069810, 2021). "Studies on the frequencies and effects of specific CYP2D6 polymorphisms have been performed in other breast cancer populations such as East and Central/South Asians; however, these studies did not report overall frequencies of patients with subtarget CSS,min ENDX." (PMID 34069810, 2021). "They concluded that CYP2D6 phenotype may have a role in the risk of developing contralateral breast cancer in patients treated with tamoxifen." (PMID 33369460, 2020). "In the first study of 297 patients with breast cancer who were genotyped for polymorphisms in CYP2D6, compared to poor metabolizers (P = .038) and extensive metabolizers (P = .011), intermediate metabolizers had significantly higher hot flash severity score after 4 months of tamoxifen treatment." (PMID 32080081, 2020). "Our observed association of high intratumoral CYP2D6 expression with favourable OS in breast cancer (BRCA) might be related to its activation of tamoxifen." (PMID 33202946, 2020). "Therefore, we sought to assessed the possible prognostic and predictive role(s) of CYP2D6 polymorphisms in metastatic and/or locally recurrent inoperable breast cancer patients from Egypt who were treated with Tamoxifen." (PMID 33369460, 2020). "Accordingly, we decided to genotype the breast cancer patients of our study for the CYP2D6 alleles ∗1, ∗2, ∗4, ∗5, ∗6, ∗10, ∗17, and ∗41 as well as the gene duplication to comprehensively cover CYP2D6 alleles representative of the Iran population (Isfahan province)." (PMID 31178724, 2019). "Overall, this study provides early evidence that the CYP2D6 phenotype may contribute to some of the observed variability in the impact of tamoxifen treatment for a first breast cancer on the risk of developing CBC." (PMID 30526633, 2018).
breast carcinoma (continued). "The results of this study suggest that the CYP2D6 phenotype could modify the association between tamoxifen treatment for a first primary breast cancer and risk of CBC." (PMID 30526633, 2018). "This study suggests that the CYP2D6 phenotype may contribute to some of the observed variability in the impact of tamoxifen treatment for a first breast cancer on risk of developing CBC." (PMID 30526633, 2018). "Using CYP2D6 as an example, we identified several SNPs that may be associated with the differential expression of CYP2D6 among CA, AA, and AS breast cancer tissues." (PMID 28684774, 2017). "Thus, genetic variation in CYP2D6 (e.g. PM status), has been associated with poor clinical outcomes in breast cancer patients treated with tamoxifen." (PMID 29868213, 2017). "In addition, breast cancer patients have CYP2D6 polymorphisms associated with loss of its enzyme function for tamoxifen metabolism." (PMID 26892504, 2016). "These available results clearly warrant further research to test the hypothesis whether CYP2D6 phenotype is associated with the clinical outcome in tamoxifen-treated breast cancer patients." (PMID 20700120, 2010). "However, the absence of an association with survival in more frequent variants, including CYP2D6*4, questions the validity of the reported association between CYP2D6 genotype and treatment response in breast cancer." (PMID 20731819, 2010). "However, the heterozygous CYP2D6 (G/A) genotype was associated with a protective effect against breast carcinoma (OR = 0.5; p = 0.02) in postmenopausal patients." (PMID 18423013, 2008). "However, patients expressing specific CYP2D6 polymorphisms (i.e., CYP2D6*3, *4, *5 and *10) that impaired or abolished CYP2D6 metabolism have a nearly 2-fold higher risk of breast cancer recurrence." (PMID 17555576, 2007). "Future prospective studies are needed to determine the frequency of other CYP2D6 alleles and copy number variations of this highly polymorphic gene in the Syrian population and investigate their potential impact on the response to tamoxifen hormonal therapy in breast cancer patients." (PMID 36243690, 2022). "A large population based case-cohort study in the United Kingdom (UK) also failed to observe an association between the common CYP2D6*4 variant and breast cancer specific survival, however, they did note that the null CYP2D6*6 allele may affect survival in patients taking tamoxifen." (PMID 29236081, 2017). "CYP2D6 *10 lost its significance when all the other SNPs were adjusted together in the multiple stepwise selection COX model, which may explain why the associations of CYP2D6 and the survival of tamoxifen-treated breast cancer patients conflict in different reports." (PMID 28178648, 2017). "Thus, transdermal treatment of LPPC/TAM might provide the breast cancer patients with CYP2D6 polymorphisms another efficient therapeutics and avoid the side effects of systemic treatment under tamoxifen administration." (PMID 26892504, 2016). "The studies on CYP2D6 polymorphisms and their influences on tamoxifen efficacy show many discrepancies, which can be accounted to multiple factors, including variations in study design, in the definitions of breast cancer disease, and in the population characteristics." (PMID 23346096, 2012). "The somewhat increased hazard of breast cancer recurrence among users of CYP2D6 inhibitors concomitantly taking tamoxifen was dependent on both the strength and proportion of overlapping time." (PMID 40364655, 2025). "In a case study, a breast cancer patient with CYP2D6 IM experienced a potent interaction between tamoxifen and rifampin, a CYP3A inducer and antibiotic." (PMID 41295207, 2025). "Our study has observed a considerably high proportion of CYP2D6 IMs among the Indonesian women with ER+ breast cancer consuming tamoxifen." (PMID 40137409, 2025).
breast carcinoma (continued). "The primary aim of the present study was to further investigate the role of CYP2D6 for the outcome in a larger cohort of tamoxifen-treated early breast cancer, accounting for adherence to tamoxifen and exposure to potent CYP2D6 inhibitors." (PMID 40600576, 2025). "The present study characterized the CYP2D6 genotypes and phenotypes in Chinese patients with breast cancer, and only CYP2D6 IM and NM were identified." (PMID 40050768, 2025). "The clinical significance of individual CYP2D6 activity for the outcome of tamoxifen treatment in early breast cancer is unclear." (PMID 40600576, 2025). "Several studies have evaluated how CYP2D6 inhibition affects tamoxifen metabolite levels and breast cancer outcomes in treated women." (PMID 40364655, 2025). "In contrast to CPIC, our findings challenge the recommendations of the ESMO Clinical Practice Guidelines for Early Breast Cancer in 2020, which recommended against the use of CYP2D6 to inform adjuvant tamoxifen decisions." (PMID 40452016, 2025). "The relationship between CYP2D6 genotype and tamoxifen efficacy is among the most extensively studied pharmacogenetic issues in breast cancer treatment." (PMID 39598531, 2024). "An analysis of patient data from China e National Cancer Center revealed that adjuvant endocrine therapy with toremifene is more effective for CYP2D6 *10 T/T breast cancer patients." (PMID 39286777, 2024). "The U.S. Food and Drug Administration (FDA) recommends CYP2D6 genotype testing for estrogen receptor-positive breast cancer patients before initiating tamoxifen treatment to optimize drug efficacy." (PMID 39598531, 2024). "In a study of TAM-treated Algerian breast cancer patients, including those genotyped as CYP2D6*17/*17." (PMID 36836506, 2023). "The role of TAM pharmacogenetics in breast cancer treatment outcomes has been extensively studied in Caucasian populations The majority of the studies found that patients with the poor CYP2D6 metabolizer status (PM) responded poorly to TAM." (PMID 36836506, 2023). "Therefore, it is reasonable to postulate that although CYP2D6 activity is diminished in IMs, the metabolic capacity of the encoded enzyme is still capable of converting tamoxifen to its active form at adequate concentrations to competitively antagonize ERs in tumor breast cancer tissues." (PMID 36243690, 2022). "We combined GWAS chip and CYP2D6 CNV data from the Breast Cancer Pain Genetics study to construct an imputation panel (n = 902) for CYP2D6 CNV." (PMID 35197553, 2022). "This study critically discusses the latest data about the role of CYP3A4, CYP2D6, and ABCB1 gene polymorphism in the regulation of doxorubicin’s effects in breast cancer patients." (PMID 36358854, 2022). "Adherence to treatment and use of co-medication, but also molecular factors such as CYP2D6 genotype, affect tamoxifen metabolism, with consequences for early breast cancer prognosis." (PMID 35455627, 2022). "The potential impact of CYP2D6 inhibition by SSRIs on clinical outcome among breast cancer patients under tamoxifen therapy become the most widely studied drug–drug interaction in breast cancer patients with co-morbid depression." (PMID 36199859, 2022). "Between 2018 and 2021, two studies provided evidence for a relation between CYP2D6 genotype and breast cancer recurrence as well as breast cancer-specific mortality after tamoxifen treatment." (PMID 33673305, 2021). "Genetic variants (CYP2D6 and CYP2C19 genotypes), tamoxifen and metabolites concentrations, baseline characteristics, and breast cancer recurrence from the CYPTAM study (NTR1509) were used." (PMID 33432065, 2021). "A good example (although still in a big debate) is genotypes of cytochrome P450 2D6 (CYP2D6) and clinical outcome of breast cancer patients treated with tamoxifen." (PMID 34121043, 2021).